OXT (oxytocin/neurophysin I prepropeptide)
Diseases named in the same sentence as OXT in open-access papers (continued):
Sharing a sentence is not in itself a finding about the gene and the disease.
personality disorder (2 papers, 2019 to 2024). A diverse category of psychiatric disorders characterized by behavior that deviates markedly from the expectations of the individual's culture; this pattern of deviation is pervasive and inflexible and is stable over time. "A recent study attested a correlation between OXT SNPs and the Personal Distress subscale of the Interpersonal Reactivity Index (a measure of dispositional empathy) in adults with personality disorders, as well as irritable aggressive anger dysfunction." (PMID 39109363, 2024).
Sjogren syndrome (2 papers, 2022 to 2024). An autoimmune disorder in which immune cells attack and destroy the glands that produce tears and saliva. "Other studies from our group showed that the MECs of chronically inflamed lacrimal glands of animal models of Sjogren’s syndrome dry eye disease had reduced size, decreased contractile protein expression, and loss of contraction in response to OXT stimulation." (PMID 38984107, 2024). "Using NOD and MRL/lpr mice (animal models of Sjogren’s syndrome), we reported a decrease in SMA and calponin protein levels plus a decline in acini contraction after stimulation with OXT." (PMID 36147586, 2022). "In our previous study, using animal models of Sjogren’s syndrome (NOD and MRL/lpr mice), we reported a decrease in SMA and calponin protein levels plus a decline in acini contraction after stimulation with OXT." (PMID 36147586, 2022). "These in vitro findings mimicked the in vivo findings we reported using animal models of Sjogren’s syndrome dry eye disease, namely, a reduction in MEC size, the degradation of contractile proteins, and the impairment of MEC contraction in response to OXT stimulation." (PMID 38984107, 2024).
steatosis (2 papers, 2013 to 2019). Increased lipid within the cytoplasm of cells. "Precious analysis revealed that ANXA2, PRKCE, and OXT are three important genes that are involved in steatosis stage of NAFLD." (PMID 31191837, 2019). "In conclusion up-regulation of OXT stimulates digestion in steatosis stage of NAFLD." (PMID 31191837, 2019). "Deregulation of ANXA2, PRKCE, and OXT is a critical event in steatosis." (PMID 31191837, 2019).
Allergy (1 paper, 2021). An allergy is an immune response or reaction to substances that are usually not harmful. "Among these, there are not only hormonal interaction phenomena that can affect OXT levels, but also possible interactions with other chemical signals, as shown by studies in which allergy sufferers have higher baseline levels of oxytocin in their blood." (PMID 34805562, 2021).
amyotrophic lateral sclerosis (1 paper, 2022). Amyotrophic lateral sclerosis (ALS) is a neurodegenerative disease characterized by progressive muscular paralysis reflecting degeneration of motor neurons in the primary motor cortex, corticospinal tracts, brainstem and spinal cord. "Summary of oxytocin (OXT) results in amyotrophic lateral sclerosis (ALS) and frontotemporal dementia (FTD)." (PMID 36187357, 2022).
Arthritis (1 paper, 2020). Inflammation of a joint. "Therefore, the precise reasons for activation of the OXT/AVP system caused by acute mono-arthritis remains unclear." (PMID 32117068, 2020). "In the present study, we evaluated the effects of acute mono-arthritis on activation of the OXT/AVP system and HPA axis using a carrageenan-induced model of knee arthritis in rats." (PMID 32117068, 2020). "Previous studies including our own used several acute/chronic nociceptive models such as the formalin test and adjuvant arthritis model in rats to examine the effects of acute/chronic nociceptive stimuli on the OXT/AVP system." (PMID 32117068, 2020). "Therefore, we aimed to simultaneously evaluate the effects of acute mono-arthritis on the activity of the OXT/AVP system and the HPA axis." (PMID 32117068, 2020). "In conclusion, the current study demonstrated that acute mono-arthritis activated ipsilateral nociceptive afferent pathways at the spinal level and simultaneously activated both the OXT/AVP system and HPA axis alongside upregulation of relevant gene expression in rats." (PMID 32117068, 2020). "Thus, it is assumed that OXT also modulates carrageenan-induced acute mono-arthritis." (PMID 32117068, 2020). "Chronic multiple-arthritis activates the OXT/AVP system, but the effects of acute mono-arthritis on the OXT/AVP system in the same animals has not been simultaneously evaluated." (PMID 32117068, 2020). "Although OXT and AVP may have anti-nociceptive effects on acute mono-arthritis, we did not conduct any pharmacological tests with OXT, AVP, or their antagonists." (PMID 32117068, 2020). "Therefore, in the present study, we decided to assess the effects of (only) arthritis without any systemic factors using the acute mono-arthritis model induced by carrageenan on the activity of OXT/AVP system as well as the HPA axis in the same animals simultaneously." (PMID 32117068, 2020).
behavioral disorders (1 paper, 2019). "Furthermore, previous studies indicated that abnormal OXT–DA interactions may contribute to behavioral disorders such as autism, sexual dysfunction, addiction and depression." (PMID 31848444, 2019).
brain tumors (1 paper, 2023). "For the other identified candidate biomarkers (EDDM3B, LMOD1, GP2, SPINT3, CTRL, OXT) there is no specific literature linking them to gliomas or other brain tumors." (PMID 36959545, 2023).
celiac disease (1 paper, 2022). An autoimmune genetic disorder with an unknown pattern of inheritance that primarily affects the digestive tract. "The most significantly up-regulated genes in celiac disease were TAP1, HLA-E, HCP5, STAT1, GBP1, STAT1, LOC100419583, and GBP4 and the down-regulated ones were IDS, PKIB, FBXO2, OXT, and ADI1." (PMID 36011206, 2022).
Chronic colitis (1 paper, 2019). A chronic inflammatory disease of the large intestine (colon, cecum and rectum). "The results showed that the expressions of OXT and OXTR were relatively high in normal tissue, and the expressions in chronic colitis, tubular adenoma, and well-differentiated CAC decreased gradually." (PMID 31920487, 2019).
diabetes insipidus (1 paper, 2022). A disorder characterized by excretion of large amounts of urine, accompanied by excessive thirst. "Animals with knockdown of Creb3l1 in the SON displayed classic signs of diabetes insipidus with increased fluid intake and the production of higher volumes of diluted urine (polyuria) compared to controls, likely due to insufficient release of AVP and OXT." (PMID 35803572, 2022).
endometritis (1 paper, 2023). An acute or chronic, usually bacterial infectious process affecting the endometrium. "OXT and AVP are important to smooth muscle contraction during parturition and lactation and are associated with endometritis, as summarized in GeneCards." (PMID 36980860, 2023).
erectile dysfunction (1 paper, 2013). Persistent or recurrent inability to achieve or to maintain an erection during sexual activity. "Consistently, erectile dysfunction in aged people with Parkinson's disease is treated by improving the function of dopamine-OXT pathway." (PMID 24967304, 2013). "Deficits in OXT-secreting system or its interactions with brain amine systems can result in loss of libido, impotence, and lack of orgasm; conversely, overactivation of these systems may cause abnormal desire and multiple orgasms." (PMID 24967304, 2013).
glioma (1 paper, 2023). A benign or malignant brain and spinal cord tumor that arises from glial cells (astrocytes, oligodendrocytes, ependymal cells). "We identified 8 plasma proteins which were increased in gliomas vs. meningiomas (GFAP, NEFL, EDDM3B, PROK1, MMP3, CTRL, GP2, SPINT3) and 4 proteins which were decreased in gliomas vs. meningiomas (FABP4, ALDH3A1, IL-12B and OXT)." (PMID 36959545, 2023).
hair loss (1 paper, 2023). "This study highlights the positive effects of OXT in hair follicles and may assist in the development of new treatments for alopecia." (PMID 37863919, 2023). "By advancing these studies, we would like to verify whether OXT can be a new drug for the treatment of alopecia." (PMID 37863919, 2023).
head and neck squamous cell carcinoma (1 paper, 2019). A squamous cell carcinoma that arises from any of the following anatomic sites: lip and oral cavity, nasal cavity, paranasal sinuses, pharynx, larynx, and salivary glands.
hypotension (1 paper, 2013). "In rats, hemorrhage and nonhypotensive hypovolemia are known to increase plasma levels of OXT and VP; arterial hypotension increases neurohypophysial release of OXT and VP." (PMID 24967304, 2013).
irritable bowel syndrome (1 paper, 2009). Irritable bowel syndrome (IBS) is a chronic functional condition of the lower gastrointestinal (GI) tract characterized by abdominal pain or discomfort and disordered bowel habit (diarrhea, constipation, or fluctuation between the two). "Genetic variants in the OXT promoter region, and in the OXTR gene in DNA samples from 131 rigorously evaluated patients with Irritable Bowel Syndrome (IBS), 408 homozygous subjects referred for lactase (LCT-13910 C>T, rs4988235) genotyping, and 299 asymptomatic blood donors were compared." (PMID 19943975, 2009).
ischemic stroke (1 paper, 2020). A stroke disorder caused by obstruction of blood flow to the brain, due to thrombotic (local blood clot formation) or embolic (due to a blood clot or other material traveling from another site) event. "The neuroprotective effect of OXT was also demonstrated in a tMCAO rat model, where it was demonstrated that the positive effects of OT on the outcomes of ischemic stroke may be associated with a reduction of calpain –1 expression." (PMID 32438751, 2020).
meningitis (1 paper, 2023). A disorder characterized by acute inflammation of the meninges of the brain and/or spinal cord. "In the group of analytes related to stress, cortisol, sAA and OXT were higher in pigs with meningitis than in healthy ones." (PMID 37525237, 2023). "Thus, the increase in OXT concentrations in pigs with meningitis found in this report, in comparison to healthy pigs, could reflect this role." (PMID 37525237, 2023).
necrotizing enterocolitis (1 paper, 2019). Necrotizing enterocolitis (NEC) is a devastating disease that affects mostly the intestine of premature infants. "Consistently, OXT can reduce necrotizing enterocolitis, a GI inflammatory disease of unknown etiology." (PMID 31920487, 2019).
neuropathic pain (1 paper, 2023). Chronic pain caused by damage to nerve fibers. "Additionally, DCZ exhibits a notably higher concentration of serum OXT and a faster onset of anti-nociceptive effect in a neuropathic pain model." (PMID 38099201, 2023).
nicotine addiction (1 paper, 2024). "In the current study, we found that the effect of OXT on the anterior rSTG under psychosocial stress was altered in smokers, likely due to the dysregulated stress responses caused by nicotine addiction, which can lead to abnormal OXT function." (PMID 39214996, 2024). "In first fMRI experiment, analysis of variance (ANOVA) revealed an interaction of OXT and nicotine addiction on subjective stress." (PMID 39214996, 2024). "Our findings revealed an interaction between OXT and nicotine addiction on subjective psychosocial stress, and identified four brain regions associated with this interaction." (PMID 39214996, 2024). "A voxel-wise ANOVA of fMRI data identified an interaction between OXT and nicotine addiction in anterior rSTG, and its functional connectivity with right middle frontal gyrus." (PMID 39214996, 2024). "Investigating the effects and interaction of OXT and nicotine addiction is essential in determining the effectiveness of OXT modulation for psychosocial stress, particularly for smokers." (PMID 39214996, 2024). "In summary, we found that nicotine addiction blocked OXT’s anxiolytic on psychosocial stress, which was related to abnormalities in anterior rSTG." (PMID 39214996, 2024). "In the current study, we identified the anterior rSTG as a site of interaction between OXT and nicotine addiction on psychosocial stress, as well as a brain region related to psychosocial stress and nicotine addiction." (PMID 39214996, 2024). "This altered relationship in smokers may indicate the neural mechanism by which OXT and nicotine addiction interact with each other in the coupling of the anterior rSTG and rMFG, thus affect subjective stress." (PMID 39214996, 2024). "However, the underlying neural mechanism of interaction between OXT and nicotine addiction on psychosocial stress has not been examined, and we conducted two experiments to reveal it." (PMID 39214996, 2024).
obsessive-compulsive disorder (1 paper, 2016). A disorder characterized by the presence of persistent and recurrent irrational thoughts (obsessions), resulting in marked anxiety and repetitive excessive behaviors (compulsions) as a way to try to decrease that anxiety. "In addition, a significant correlation between the basal OXT levels and the baseline ratings of the Yale–Brown Obsessive-Compulsive Scale has been demonstrated in individuals with obsessive-compulsive disorder, which sometimes co-occurs with ASD." (PMID 26834651, 2016).
ovarian carcinoma (1 paper, 2022). A malignant neoplasm originating from the surface ovarian epithelium. "OXT inhibited ovarian cancer metastasis by suppressing the expression of MMP-2 and VEGF." (PMID 36172369, 2022).
pituitary tumor (1 paper, 2021). A benign or malignant neoplasm affecting the pituitary gland. "OXT is produced in the paraventricular nucleus (PVN) and supra-optic nucleus (SON) of the hypothalamus, thus OXT deficiency is plausible in individuals with hypothalamic and pituitary tumors." (PMID 34646154, 2021).
Polydipsia (1 paper, 2025). Excessive thirst manifested by excessive fluid intake. "AVP loss typically presents with the polyuria and polydipsia of CDI, whereas OXT deficiency manifests more subtly through alterations in emotional regulation, feeding behavior, and social cognition." (PMID 41614746, 2025).
retinal diseases (1 paper, 2024). "We hypothesized that perinatal OXT administration might influence the development of the neural retina and its vasculature, offering therapeutic potential for retinal diseases such as retinopathy of prematurity (ROP)." (PMID 39451253, 2024).
Rett syndrome (1 paper, 2024). A severe neurodevelopmental disorder affecting the central nervous system. "For instance, OXT treatment has been shown to restore KCC2 expression and E/I balance in a mouse model of Rett syndrome." (PMID 39469188, 2024).
Schaaf-Yang syndrome (1 paper, 2023). "In the Magel2-knockout (KO) mouse, a model of Schaaf-Yang Syndrome, an early postnatal administration of OXT rescued autistic-like behavior and cognition at adulthood, making this model relevant for understanding the actions of OXT in (re)programming postnatal brain development." (PMID 36998737, 2023). "However, the main aim of this study was to investigate the effect of early postnatal OXT treatment in male and female Magel2-KO mice in order to advance the translational research on OXT treatment for Schaaf-Yang Syndrome and Prader-Willi patients." (PMID 36998737, 2023).
small cell lung carcinoma (1 paper, 2019). Small cell lung cancer (SCLC) is a highly aggressive malignant neoplasm, accounting for 10-15% of lung cancer cases, characterized byrapid growth, and early metastasis. "Intranasal OXT application to F1 rat dams was reported to increase serum interferon-γ level in F2 juvenile female offspring, which is associated with apoptosis of small-cell lung cancer." (PMID 31920487, 2019).
psychiatric disorder (31 papers, 2010 to 2026). A disorder characterized by behavioral and/or psychological abnormalities, often accompanied by physical symptoms. "Overall, while some research questions involved in OXT/OXTR deficiency-related psychiatric disorders have been answered, many others remain to be addressed." (PMID 37153633, 2023). "Although the mechanisms underlying the aggression involved in psychiatric disorders remain unclear, emerging evidence showed the involvement of the OXT/OXTR signal in aggression." (PMID 37153633, 2023). "Moreover, decreased OXT system activity may lead to the development of social withdrawal in MDD and also increase the risk of psychiatric disorders (see also OXT and social interactions in clinical section)." (PMID 27713275, 2010). "Targeting dose-dependent OXT signaling is a potential therapeutic strategy for women with psychiatric disorders." (PMID 41756013, 2026). "Nonetheless, here, we summarized the aberrant OXT/OXTR signaling in the pathogenesis of the following psychiatric disorders or alterations in brain function." (PMID 37153633, 2023). "Lastly, recent (last months of 2022) reviews present OXT as having the potential to become a key therapeutic agent for future treatment and prevention strategies concerning the main psychiatric disorders." (PMID 36358953, 2022). "In the third part, we outline OXT’s potential role in the development of novel clinical interventions and the implications for treating psychiatric disorders characterized by social dysfunction." (PMID 32981445, 2021). "These behaviors are at the very basis of more complex social behavior, and are often affected in psychiatric disorders that are associated with both ES and AVP/OXT and can be and have been reliably assessed in rodents." (PMID 31404254, 2019). "In all, OXT has a great potential to ameliorate social dysfunction in a broad range of psychiatric disorders." (PMID 31998152, 2019). "Recent studies are currently examining OXT’s potential beneficial effects on social cognition in conditions other than psychiatric disorders." (PMID 31998152, 2019). "This review summarizes findings on the associations between OXT and AVP receptor polymorphism, social behavior, and psychiatric diseases." (PMID 26858594, 2015). "Plasma OXT levels are also decreased in cocaine-addicted mothers who are more likely to have psychiatric disorders and less attachment to their infants." (PMID 27713275, 2010). "Finally, current biological strategies to augment the level of OXT in stress-related neuropsychiatric disorders were summarized, shedding a light on the treatment of stress-induced psychiatric disorders." (PMID 38017588, 2023). "Therefore, it is possible that adverse early-life experiences resulted in altered activity of the brain OXT system in adulthood, especially its receptors, and thereby, increase the likelihood of developing mental disorders." (PMID 27713275, 2010). "Together with the studies assessing plasma OXT, these findings suggest that the OXT system may be dys-regulated in psychiatric disorders." (PMID 27713275, 2010). "Future clinical studies could examine whether OXT could be of therapeutic value in PPD, and longer term to less the risk of the development of psychiatric disorders in the children of such mothers." (PMID 27713275, 2010). "Consequently, OXT is considered a promising neuromodulator for therapeutic strategies targeting stress-induced psychiatric disorders and mental illnesses, which may result from chronic stress influencing dopaminergic dysregulation." (PMID 39607552, 2024). "Here we summarize the expression of OXTR and the involvement of OXT/OXTR signaling in the regulation of intracellular effects, behavioral responses, functional alterations, and the outcomes of OXTR dysregulation or deficiencies in behavioral deficits and psychiatric disorders." (PMID 37153633, 2023).